RNY3P8 (RNY3 pseudogene 8)
Gene: Miscellaneous RNA gene on chromosome 13 (95,310,830 to 95,310,955, reverse strand). Ensembl gene ENSG00000223298.
Homologues: Orthologues: chimpanzee Y_RNA (99% identical), guinea pig Y_RNA (56% identical). Paralogues in human: Y_RNA (59% identical), Y_RNA (58% identical), Y_RNA (57% identical), RNY3 (56% identical), Y_RNA (56% identical), RNY3P1 (56% identical), RNY3P4 (55% identical), Y_RNA (55% identical), RNY3P13 (54% identical), RNY3P5 (54% identical), RNY3P9 (54% identical), Y_RNA (54% identical), and 75 more.